IL18 (interleukin 18)
Diseases named in the same sentence as IL18 in open-access papers (continued):
Sharing a sentence is not in itself a finding about the gene and the disease.
infection (continued). "Composed of the sensor protein NLRP3, the adaptor protein ASC, and pro-caspase-1, it recognizes cellular damage and infections, triggering the release of pro-inflammatory cytokines like IL-1β and IL-18, and inducing pyroptosis." (PMID 40688353, 2025). "Interestingly, other researchers also linked IL-18 to disease severity caused by L. (L.)amazonensis, as IL-18-deficient mice developed smaller lesions and lower parasite loads compared to wild-type animals, suggesting this cytokine’s contribution to host susceptibility to infection." (PMID 40431153, 2025). "At both 24 and 96 h post‐infection, levels of IL‐1β, IL‐18, and IL‐12 were significantly higher in the Y‐infected group compared to all other groups." (PMID 40940710, 2025). "Low levels of IL-18 release were exclusively observed in cell supernatants following Brazil/78 infection (~2-fold)." (PMID 40481027, 2025). "Conversely, IL-18 levels - which were initially elevated in uninfected macrophages - declined markedly following infection, with a statistically significant reduction observed particularly in samples from male-derived macrophages." (PMID 40794782, 2025). "IL-18 has been shown to have a protective role following CR infection, as Il18-/- mice presented greater bacterial load and exacerbated histopathology." (PMID 40591723, 2025). "Instead, these cells respond to inflammatory signals, such as cytokines like IL-12 and IL-18, during infections or immune responses." (PMID 41438743, 2025). "Recent studies have highlighted the critical role of IL-18 in modulating ILC3s function during CR infection." (PMID 40591723, 2025). "The same work described that BALB/c mice exposed to a low dose of LPS prior to IAV H1N1 (A/Fort Monmouth/1/1947) infection exhibited reduced weight loss, lung injuries, and respiratory levels of TNF-α, IL-6, and IL-18." (PMID 40565228, 2025). "In our future experiments, we intend toinvestigate the relationship between cytochrome P450 and IL18 in Mac_CD163 duringASFV infection." (PMID 39932318, 2025). "Macrophage-derived IL-1β and IL-18 play pivotal roles in recruiting other immune cells, particularly adaptive ones, to the sites of infection." (PMID 41208996, 2025). "In the case of cytokines, their relationship with infection is more unequivocally established, and IL‐1β, IL‐18, MIG, and IP‐10 have been related to COVID‐19." (PMID 39800769, 2025). "This complex drives the maturation and release of inflammatory cytokines such as IL-1β and IL-18, which promote further immune activation and recruit additional immune cells to the site of injury or infection." (PMID 40688353, 2025). "Quantitative PCR was performed to assess the expression levels of Tnf-α, Il-1β, and Il-18 in liver and spleen tissues at 7, 14, and 21 days post-infection." (PMID 40892762, 2025). "The expression of IL-1β, IFN-α2, IFN-γ, TNF-α, MCP-1 (CCL2), IL-6, IL-8 (CXCL8), IL-10, IL-12p70, IL-17A, IL-18, IL-23, and IL-33 was assessed in apical washes at different time points after infection using a 13-plex immunoassay." (PMID 40143308, 2025). "In contrast, H37Rv infection significantly upregulated IL18, whereas downregulating IL6, both of which are prominent proinflammatory cytokines." (PMID 40738187, 2025). "In the case of MHV-JHM infection, changes in expression (from 0% to 100%) were visible in IL-6, IL-18, IL-33, ENA-78 (CXCL5), GRO alpha (CXCL1), IP-10 (CXCL10), MCP-1 (CCL2), MIP-1 beta (CCL4), MIP-2 alpha (CXCL2), RANTES (CCL5), and TNF alpha." (PMID 40358160, 2025). "In the spleen, Tnf-α was elevated only on day 14 post-infection, while both Il-1β and Il-18 showed a decreasing trend throughout the infection period." (PMID 40892762, 2025). "- Functionally similar.- Produce IL-12 and IL-18 (~48 h post-infection).- Participate in immune regulation and tolerance via alternative activation." (PMID 41479896, 2025).
infection (continued). "Enzyme-linked immunosorbent assay (ELISA) demonstrated a significant and sustained increase in circulating IL-1β and IL-18 levels during 5–14 days post-infection (dpi), consistent with a systemic inflammatory response." (PMID 41334910, 2025). "The protein expression of three proteins (IL-17C, IL-18, and IL-10RB) was significantly decreased in caspase-1-deficient cells compared to Cas9 cells following HK1651 infection." (PMID 40137780, 2025). "In summary, TNF, IL-8, and IL-10 specifically increased following infection, whereas CCL2 and IL-18 showed an infection-dependent reduction." (PMID 40794782, 2025). "Caspase-1- and caspase-4-deficient cells showed significantly altered cytokine and chemokine profiles after infection with A. actinomycetemcomitans, showing reduced IL-17C and IL-18 release." (PMID 40137780, 2025). "Taken together, our findings underscore that while TRIM29 is dispensable for barrier integrity, its deficiency in IECs restricts infections by enteric RNA viruses by enhancing IFN-λ3 and IL-18 production in primary IECs from mouse intestinal organoids." (PMID 39396665, 2025). "We found that Tnf-α, Il-1β, and Il-18 were markedly upregulated in liver tissue, especially in the early phase of infection, supporting a role for robust local inflammation in mediating hepatocellular injury." (PMID 40892762, 2025). "To further investigate the role of IL-18 in driving ILC2 expansion, we used Il22-/- mice, which show reduced IL-18 expression during CR infection." (PMID 40591723, 2025). "ISG15 acts synergistically with IL-18 cytokine to increase the IFN-γ production by NK cells early after infection, which is critical for the rapid establishment of innate IFN-γ immunity and efficient clearance of the bacterial pathogen." (PMID 40627782, 2025). "We detected the expression of major inflammasome genes (NLRP3, caspase-1, IL-1β, IL-18) during infection progression." (PMID 40906404, 2025). "Caspase-1 cleaves pro-inflammatory cytokines, particularly IL-1β and interleukin-18 (IL-18), into their active forms, which are then released from the cell to propagate inflammation and recruit additional immune cells to the site of infection or injury." (PMID 40141426, 2025). "After four days of infection with either one of the two SARS‐CoV‐2 virus variants, increasing concentrations of IL‐18 became recognizable." (PMID 40887824, 2025). "In contrast, the spleen displayed suppressed expression of Il-1β and Il-18 throughout the course of infection, despite demonstrating biochemical markers of injury." (PMID 40892762, 2025). "In contrast, interleukin-18 (IL-18) levels were lower (padj<0.05) in the early infection group compared to the unexposed group." (PMID 41510260, 2025). "The production of key cytokines (IL‐1β, IL‐18, IL‐6, IL‐10, IL‐12) and nitric oxide (NO) was quantified at 24 to 96 h post‐infection." (PMID 40940710, 2025). "Of these, CCL20, CXCL10, CXCL1, CXCL8, and IL-18 showed higher levels compared to uninfected epithelium 24 h after infection." (PMID 40586572, 2025). "IL-18 is a potent pro-inflammatory cytokine involved in host defense against infections and the regulation of both innate and adaptive immune responses." (PMID 40507498, 2025). "The next step was to evaluate the participation of IL-18 in the control of infection by F. pedrosoi." (PMID 40315193, 2025). "In terms of modulating early immune responses, IFN-γ, IL-1α, and IL-12p70 are crucial for infection control, while IL-13 and IL-18, found at higher levels in P4, assist in tissue repair and maintaining an anti-inflammatory environment." (PMID 40046233, 2025). "In our model, EV71 infection resulted in elevated levels of pro-IL-1β, cleaved IL-1β, and IL-18 in brain tissue, peaking on day 10 post-infection." (PMID 41288075, 2025).
infection (continued). "Treating mice with IL-18 BP at days 2 and 3 post-CR infection inhibited ILC2s expansion, and treating Il22-/- mice with rIL-18 rescued ILC2s expansion, together providing direct evidence that IL-18 plays a key role in ILC2s expansion during infection." (PMID 40591723, 2025). "Silencing of the gene encoding NLRP7 in human macrophages leads to a reduction in IL-1β and IL-18 release during infection with the bacterium S. aureus or L. monocytogenes, suggesting that NLRP7 activation mediates an inflammasome response." (PMID 41062723, 2025). "Recent studies have shown the importance of IL-18 for the resistance to infection by many pathogens, including Paracoccidioides brasiliensis, Burkholderia pseudomallei and Streptococcus pneumoniae." (PMID 40315193, 2025). "They respond to a wide range of stimuli, including cytokines produced by infected and myeloid cells (most prominently type I IFN, IL-12 and IL-18) as well as signals indicating cellular stress, infection, or oncogenic transformation." (PMID 40627782, 2025). "Epithelial cells produce IL-18 in response to Ct infection and we observed elevated IL-18 levels in supernatants of infected mFGT organoids from WT and ISG15−/− mice." (PMID 40627782, 2025). "The NLRP3 inflammasome is composed of NLRP3, ASC, and pro-caspase-1, regulating the activation of caspase-1 and following the release of IL-1β and IL-18 from innate immune cells during infection or damage." (PMID 40872501, 2025). "In experiments with a mouse burn model, IL-18 knockout mice presented a 35% reduction in infection rates." (PMID 41376789, 2025). "Our findings add a new dimension to this pathway by demonstrating that IL-18 also regulates ILC2s expansion in the early phase of CR infection." (PMID 40591723, 2025). "Injection of IL-18 binding protein (IL18 BP), at 2- and 3-days post CR infection, blocked expansion of ILC2s in vivo." (PMID 40591723, 2025). "For instance, at the site of infection, various cytokines, such as IL-7, IL-12, IL-15, and IL-18, directly activate MAIT cells." (PMID 38419084, 2024). "Interleukins are the most important cytokines released during infection, which include IL-1β, IL-18, IL-6, IL-12, and IL-17." (PMID 39042701, 2024). "This characteristic is particularly beneficial in situations where treatment must be urgently discontinued to allow IL-18 to perform its role, such as combating a life-threatening infection." (PMID 39769266, 2024). "A similar increase in IL-18 was observed 6 days post-treatment in the repeat blood stage infection study and its expression pattern correlated with activated CD4+ and activated regulatory T cells." (PMID 38890271, 2024). "Taken together, these results show that Ascaris suppresses IFN-γ production by NK cells during single infection, but also in pigs concurrently infected with Ascaris and Salmonella in response to IL-12 and IL-18 stimulation." (PMID 38918457, 2024). "Luminal content from the ceca of IL-18 treated Il22−/− mice contained greater amounts of Muc2 protein after infection, suggesting local goblet cells released more Muc2 in response to IL-18 treatment." (PMID 39428744, 2024). "Functionally, NKB cells have been described as expressing several cytokines, including IL-1b, IL-6, IL-12, and IL-15, upon stimulation/infection, in addition to their signature IL-18 secretion." (PMID 38739675, 2024). "Our data also show that IL18 levels are also significantly higher in N. caninum-infected mice at 4 h post-infection, and IL18 levels generally track with IFNγ (Data Set S1)." (PMID 39445806, 2024). "We also recorded a reduction in the level of IL-18 mRNA expression after L. europaeus infection (both genotypes), with a stronger expression in the GI.2 infection group (5.1-fold reduction) and GI.1 (3-fold reduction)." (PMID 39273479, 2024). "With IL-18 being a molecule released downstream of caspase-1, we were curious as to when during infection IL-18 is released." (PMID 39446964, 2024).
infection (continued). "The infection-dependent potentiation of IL-18 release from both untreated and IFNγ-primed cells was statistically significant." (PMID 39254346, 2024). "In the current study, we treated BC 5,637 cells with LPS to mimic the inflammatory microenvironment caused by infection and found that LPS notably increased the levels of NLRP3 and inflammatory cytokines, including IL-1β, IL-18, and TNF-α." (PMID 39144184, 2024). "As first responders to infection, they secrete IL-18 to induce a critical cascade of innate and adaptive immune cell infiltration and activation." (PMID 38739675, 2024). "This activation leads to the cleavage of proinflammatory cytokines, including interleukin-18 (IL-18) and IL-1β, crucial in combating the infection." (PMID 38399676, 2024). "Surprisingly, the results showed that only IL-1β and IL-18 levels were significantly higher in cells infected with B. pseudomallei than those infected with B. thailandensis at 3 and 6 h post-infection." (PMID 39042701, 2024). "IL-18 plays a significant role in regulating the immune response, particularly in the context of inflammation, infection, and immune cell communication." (PMID 38745971, 2024). "In a healthy immune system, IL-18 plays a beneficial role in the host defense against infections and in the regulation of immune responses aimed to maintain homeostasis." (PMID 39769266, 2024). "Similar to memory CD8+ T cells, CD4+ TIA cells can be stimulated in vitro to produce IFN-γ by the cytokine combination IL-12 + IL-18, both of which are present during Lpn infection." (PMID 38838013, 2024). "Inflammasomes serve as a platform for the activation of caspase 1, an enzyme that cleaves proinflammatory cytokines, interleukin 1β (IL1β) and IL18, converting them into their active forms during an infection by M. tb." (PMID 39125766, 2024). "Infection with M84stop MCMV resulted in significantly higher IL-18 levels compared to infection with WT MCMV." (PMID 38278864, 2024). "This intervention involves inhibiting the inflammasome pathways, which play a pivotal role in the production of IL1β and IL18 cytokines during infections by M. tb." (PMID 39125766, 2024). "The administration of neutralizing antibodies to cytokines IL-18 and IL-12 exacerbated infection in mice." (PMID 38667922, 2024). "This is an intriguing model given that IL18 levels are higher in N. caninum-infected mice as early as 4 h post-infection." (PMID 39445806, 2024). "While we did not detect vaccination-associated differences in plasma levels for IL-5, IL-23, IL-33, and CCL2/MCP-1, we observed a step-wise reduction of IL-18 levels after post-infection vaccinations in individuals with ongoing PCC." (PMID 38316833, 2024). "IL-18 is responsible for the induction of adaptive immune responses after innate immune responses, and it is assumed to play an important role in anti-infection defence." (PMID 39431236, 2024). "The release of IL-1β and IL-18 swiftly initiates immune responses, eliciting chemical signals at the site of infection and recruiting macrophages, neutrophils, and other inflammatory cells." (PMID 38399989, 2024). "mRNA levels of Il1β, Tnf and Il18 were significantly increased in the acute phase of the infection compared to those in uninfected salivary gland tissue." (PMID 39355243, 2024). "Nevertheless, we observed that PCC patients who were vaccinated post-infection less frequently reported gastrointestinal symptoms and had lower levels of IL-1β and IL-18." (PMID 38316833, 2024). "Several proinflammatory cytokines are secreted during the adaptive phase, such as TNF-α, IFN-γ, IL-1β, IL-12, and IL-18 which together form an inflammatory response regulating parasite growth and infection outcome." (PMID 38623843, 2024). "Compared with the control group, the Pm challenge group showed significantly increased PARP1, HMGB1, IL-1β, and IL-18 protein expression in the blood vessels, indicating that Pm infection in mice triggered vascular inflammatory injury." (PMID 39850582, 2024).
infection (continued). "This inflammasome dependency was mediated through the cytokines, IL-18 and IL-22, as they were necessary for the infection-induced thickening of the b1 mucus layer in the distal colon." (PMID 39428744, 2024). "In a murine model of infection with the nematode Nippostrongylus brasiliensis, IL-13 was shown to inhibit the expression of IL-18, an inflammasome-activated cytokine that contributes to inflammation a cell death via pyroptosis." (PMID 38374922, 2024). "The infection of macaques with HTLV-1WT or HTLV-1p12KO was associated with higher plasma levels of IL-10 after 21 weeks, while IL-6, IFN-γ, IL-18, and IL-1β were only elevated in animals infected with HTLV-1WT." (PMID 38668247, 2024). "Our report is the first to show the expression profile of inflammatory biomarkers (IL-1β, IL-6, TNF-α, IL-18) in four tissues after infection with L. europaeus—with two genotypes simultaneously." (PMID 39273479, 2024). "As expected, gnotobiotic chicks with S. Typhimurium infection showed multiple fold increase in the expression levels of various pro-inflammatory cytokines and chemokines; IL-18, IL-1β, IL-6, and IL-8L1 at day 5 post-infection." (PMID 38315031, 2024). "The serum concentrations of RANTES, IL-18, IL-23, and IgG4 were higher in all children with recurrent infections vs. those of the CG (p < 0.001)." (PMID 39431236, 2024). "The invasive pathogen Shigella flexneri (S. flexneri) is accompanied by the release of inflammatory cytokines IL-1β and IL-18 during the infection stage." (PMID 38019021, 2024). "As a crucial component of the innate immune system, inflammasomes are activated by cellular infection or stress, which leads to the secretion of proinflammatory cytokines IL-1β and IL-18." (PMID 38891697, 2024). "We also observed a significant rise in the levels of inflammatory factors, such as IL-18 and IL-1β, in the serum of infected mice, with the ZB-1 group showing significantly higher levels than the ZB-1Δirp2 group, peaking 24 hours after infection." (PMID 37511208, 2023). "Key innate inflammatory cytokines, including TNFα, IL-6, IFNα, IL-10, IL-15, and IL-18, were all significantly elevated early during infection (days 1–5) compared to HCs." (PMID 36752598, 2023). "RSV induces the activation of the NLRP3 inflammasome and caspase 1, and both events are crucial for the secretion of IL-1β, IL-33, and IL-18 during infection." (PMID 37508374, 2023). "In this study, we found that the protein levels of the inflammasome signaling protein caspase-1, ASC, IL-1β and IL-18 were elevated during COVID-19 infection and remained elevated even after the active infection was over." (PMID 37168848, 2023). "ST infection markedly improved the mRNA relative expression levels of inflammasome biomarkers including Caspase-1, IL-1β and IL-18 compared with the control group (p < 0.05)." (PMID 37893938, 2023). "The NLRP3 inflammasome is a critical component of the immune system that mediates caspase-1 (Casp1) activation and the secretion of the pro-inflammatory cytokines, interleukin (IL)-1β and IL-18, in response to infection and cell injury." (PMID 36894537, 2023). "A group of NLRs are associated with the formation of the inflammasome, a cytosolic multiprotein complex that, once activated, induces the production of IL-1β and IL-18 and the recruitment of immune cells to the site of infection." (PMID 37243291, 2023). "As the key players in the regulation of inflammatory processes, the expression levels of IL-1β and IL-18 were measured in vivo and in vitro to explore the relationship between YT strain infection and inflammation." (PMID 37063902, 2023). "Inflammasome activation and secretion of IL-1β/IL-18 following infection with M. ulcerans strain Agy99, M. marinum, or M. pseudoshottsii were also completely abolished in ASC-deficient macrophages." (PMID 37910490, 2023).